PLOD3 (procollagen-lysine,2-oxoglutarate 5-dioxygenase 3)
Description:
Multifunctional enzyme that catalyzes a series of essential post-translational modifications on Lys residues in procollagen. Plays a redundant role in catalyzing the formation of hydroxylysine residues in -Xaa-Lys-Gly-sequences in collagens. Plays a redundant role in catalyzing the transfer of galactose onto hydroxylysine groups, giving rise to galactosyl 5-hydroxylysine. Has an essential role by catalyzing the subsequent transfer of glucose moieties, giving rise to 1,2-glucosylgalactosyl-5-hydroxylysine residues. Catalyzes hydroxylation and glycosylation of Lys residues in the MBL1 collagen-like domain, giving rise to hydroxylysine and 1,2-glucosylgalactosyl-5-hydroxylysine residues. Essential for normal biosynthesis and secretion of type IV collagens (Probable). Essential for normal formation of basement membranes (By similarity).
Synonyms: LH3; BCARD
Tractability: Small molecule: a structure with a bound ligand is known. Antibody: UniProt places it where antibodies can reach, with high confidence; UniProt predicts a signal peptide or a membrane-spanning region; its Gene Ontology location is reachable by antibodies, with medium confidence. PROTAC: ubiquitination databases record sites on it; its protein half-life has been measured; a small molecule that binds it is known.
Target class: Enzyme; Oxidoreductase
Gene: Protein-coding gene on chromosome 7 (101,205,977 to 101,219,968, reverse strand). Ensembl gene ENSG00000106397.
Subcellular location: Rough endoplasmic reticulum; Endoplasmic reticulum lumen; Endoplasmic reticulum membrane; Secreted; Secreted, extracellular space
Pathways (Reactome):
Extracellular matrix organization: Collagen biosynthesis and modifying enzymes
Gene Ontology:
Molecular function: iron ion binding; metal ion binding; procollagen galactosyltransferase activity; procollagen glucosyltransferase activity; procollagen-lysine 5-dioxygenase activity; protein binding; small molecule binding; L-ascorbic acid binding; oxidoreductase activity, acting on paired donors, with incorporation or reduction of molecular oxygen
Biological process: collagen biosynthetic process; protein O-linked glycosylation via galactose; collagen fibril organization
Cellular component: endoplasmic reticulum; endoplasmic reticulum lumen; extracellular exosome; extracellular region; Golgi apparatus; rough endoplasmic reticulum; endoplasmic reticulum membrane; extracellular matrix; trans-Golgi network
Genetic constraint (gnomAD): Loss-of-function variants: 67 observed, 88.72 expected, observed/expected ratio (o/e) 0.76, 90% interval 0.62 to 0.93. The upper end of that interval is the gene's LOEUF score, 0.93, which puts it in group 3 of 6, group 1 being the genes least tolerant of losing a copy. Missense variants: 983 observed, 978.25 expected, observed/expected ratio (o/e) 1, 90% interval 0.95 to 1.06. Synonymous variants: 442 observed, 392.65 expected, observed/expected ratio (o/e) 1.13, 90% interval 1.04 to 1.22.
Homologues: Orthologues: chimpanzee PLOD3 (99% identical), macaque PLOD3 (98% identical), pig PLOD3 (94% identical), mouse Plod3 (91% identical), rat Plod3 (91% identical), dog PLOD3 (87% identical), guinea pig PLOD3 (85% identical), tropical clawed frog plod3 (68% identical), zebrafish plod3 (64% identical), Drosophila melanogaster Plod (45% identical), Caenorhabditis elegans let-268 (44% identical). Paralogues in human: PLOD1 (58% identical), PLOD2 (58% identical), COLGALT2 (18% identical), COLGALT1 (18% identical), CERCAM (17% identical).
Diseases named in the same sentence as PLOD3 in open-access papers:
PLOD3 is named in the same sentence as 77 diseases in open-access papers, as found by Europe PMC text mining. Sharing a sentence is not in itself a finding about the gene and the disease. The quoted sentences say what the papers report.
glioma (18 papers, 2018 to 2024). A benign or malignant brain and spinal cord tumor that arises from glial cells (astrocytes, oligodendrocytes, ependymal cells). "The association of PLOD3 with poor prognosis has been found in ovarian cancer, gastric cancer, and glioma." (PMID 34239923, 2021). "PLOD3 is a novel diagnostic marker for early-stage hepatocellular carcinoma, human glioma prognosis and ovarian cancer." (PMID 34646265, 2021). "Overexpression of the PLOD3 gene, which encodes a lysyl hydroxylase, significantly promotes the progression of gliomas and is associated with a poor prognosis in glioma patients." (PMID 34559584, 2021). "Both PLOD2 and PLOD3 had been reported to be highly expressed in gliomas and were associated with tumor progression and prognosis." (PMID 34040895, 2021). "PLOD3 was found to be highly expressed in lung cancer and gliomas, which is associated with poor prognosis of them." (PMID 32547879, 2020). "To determine PLOD3 expression in glioma tissues, we first analyzed the association between PLOD3 expression and pathological grading of human gliomas using the GEO database (GSE4290)." (PMID 29644003, 2018). "Next, we examined the underlying PLOD3 mechanism in glioma, including EMT markers and the PI3K/AKT/mTOR signaling pathway, which has been reported to play a critical role in regulating angiogenesis in glioma." (PMID 29644003, 2018). "Our data confirm that elevated PLOD3 mRNA expression is associated with high-grade gliomas and unfavorable prognosis in two different datasets, GSE16011and GSE13041." (PMID 29644003, 2018). "PLOD3 is a multifunctional enzyme with lysyl hydroxylase, collagen galactosyltransferase as well as glucosyltransferase ability and is highly expressed and associated with the progression of lung cancer, glioma, ovarian cancer, gastric cancer, hepatocellular cancer and pancreatic cancer." (PMID 34585630, 2021). "Bioinformatics analysis based on TCGA/CGGA and cell function experiments suggested that PLOD3 function as an oncogene in glioma progress." (PMID 39431006, 2024). "According to the results of the CCK-8 assay, down-regulated level of PLOD3 expression significantly restrained the proliferation ability of glioma cells compared with control group." (PMID 35788194, 2022). "To reveal malignant behaviors of the hub gene modulating m7G modification patterns of glioma, we first validation biological behaviors of down-regulated expression of hub gene, PLOD3, in LN18 and T98G cells." (PMID 35788194, 2022). "For instance, recent evidence showed that elevated PLOD3 promotes gliomas' malignant characteristics and poor prognosis." (PMID 35528238, 2022). "The LH3/PLOD3 isoform was identified to be upregulated in glioma, gastric cancer and colorectal cancer, acting as a promoter of metastatization in different cancer types." (PMID 36090047, 2022). "Overall, the down-regulation of PLOD3, the hub gene modulating m7G modification patterns, significantly suppressed proliferation and migration capacity of glioma cells." (PMID 35788194, 2022). "As we guessed, the down-regulation of PLOD3 significantly inhibited the proliferation and migration of glioma cells." (PMID 35788194, 2022). "Transwell cell migration assay also indicated that the down-regulation level of PLOD3 expression significantly inhibited the metastasis ability of glioma cells compared with control group." (PMID 35788194, 2022). "For example, PLOD3 can promote lung cancer metastasis by regulating STAT3, and PLOD3 silencing can inhibit the proliferation of glioma cells via P21 pathway." (PMID 34576068, 2021). "Both PLOD2 and PLOD3 had been reported to be highly expressed in gliomas, while the prognostic value of PLOD1 remains to be further illustrated, so we want to investigate the PLOD1 expression in glioma and its clinical implication." (PMID 34040895, 2021). "Two independent studies have reported PLOD3 mRNA overexpression in glioma and hepatocellular carcinoma tissues." (PMID 30770789, 2019).
glioma (continued). "PLOD3, which we identified as a radioresistance-related protein, has already been highlighted for its potential role in hepatocellular carcinoma, glioma, skin cancer, and prostate cancer." (PMID 30770789, 2019). "We surveyed PLOD3 expression in 2 glioma datasets (GSE16011 and GSE13041) from the SurvExpress database." (PMID 29644003, 2018). "PLOD3 mRNA and protein expression were upregulated in glioma tissues compared to normal brain tissues." (PMID 29644003, 2018). "We further performed western blotting to quantitate the PLOD3 protein level in human glioma cell lines and normal brain tissue." (PMID 29644003, 2018). "The wet lab results, including RT-PCR and western blotting, demonstrated overexpression of PLOD3 in human glioma cells." (PMID 29644003, 2018). "After 2 weeks of tumor cell transplantation, the PLOD3 knockdown glioma cells developed significantly smaller tumors compared with PLOD3 wild-type cells." (PMID 29644003, 2018). "Overexpression of PLOD isoforms has been demonstrated to act as a critical role in tumor migration via modification of collagen networks in human cancer experiments, but the role of PLOD3 in glioma is poorly studied." (PMID 29644003, 2018). "Taken together, these discoveries reveal that PLOD3 is a potential therapeutic target in human gliomas." (PMID 29644003, 2018). "Inhibition of PLOD3 in glioma cells decreased VEGF expression, migration and invasion by downregulating mesenchymal markers, including Snail and Twist." (PMID 29644003, 2018). "Our data suggest that type IV, V, and VI collagen expression was largely unchanged after PLOD3 knockdown in glioma cells." (PMID 29644003, 2018). "After successful generation of stable PLOD3 knockdown glioma cells, we investigated cell proliferation in GBM cells." (PMID 29644003, 2018). "To explore the mechanism by which PLOD3 contributes to glioma tumorigenesis, we knocked down PLOD3 expression in GBM8401 and LN229 cells using siRNA." (PMID 29644003, 2018). "Knockdown of PLOD3 decreased the number of active proliferating cells compared with siControl glioma cells." (PMID 29644003, 2018). "However, several recent studies on PLODs in cancer suggest that PLOD3 plays an important role in a variety of cancer types, such as in lung and gastric cancer, glioma, and sarcoma." (PMID 39530057, 2024). "Previous studies have revealed that PLOD2 and PLOD3 have predictive effects on the prognosis of glioma, we speculated that PLOD1 also influence the prognosis of glioma, although it has not been explored." (PMID 34040895, 2021). "The expression of PLOD3 is a noteworthy biomarker for human glioma prognosis." (PMID 29644003, 2018). "These preliminary results suggested that PLOD3 is a potential biomarker for glioma." (PMID 29644003, 2018). "Our study result demonstrated that PLOD3 silencing inhibits glioma cell migration that could be categorized as type 3 EMT due to suppressing Snail and Twist expression, but no change of Vimentin." (PMID 29644003, 2018). "We hope this PLOD3 study provides valuable insight into novel therapeutic stratagems for glioma." (PMID 29644003, 2018). "Our data established PLOD3 overexpression in high-grade gliomas." (PMID 29644003, 2018). "We investigated the clinical use of PLOD3 for determining glioma prognosis." (PMID 29644003, 2018). "Therefore, we designed an orthotopic xenograft in vivo study to investigate the role of PLOD3 in glioma invasion." (PMID 29644003, 2018). "In this study, there are inconsistent expression of EMT markers between glioma cells treated with siPLOD3 and shPLOD3 which may be explained by the cells’ response to acute and long-term knockdown of PLOD3." (PMID 29644003, 2018). "Finally, our data demonstrated that PLOD3 is a potential prognostic biomarker and therapeutic target in human gliomas." (PMID 29644003, 2018).
glioma (continued). "Because PLOD3 is a collagen-modifying enzyme, we were interested in knowing whether PLOD3 knockdown would influence type IV, V, and VI collagen levels in glioma cells." (PMID 29644003, 2018). "PLOD3, a collagen biosynthesis-related protein, was reported to contributes to carcinogenesis of HCC, glioma, ovarian cancer, and lung cancer." (PMID 34646265, 2021). "Moreover, higher PLOD3 expression was associated with negative survival in glioma patients." (PMID 29644003, 2018). "Furthermore, rescue experiments validated that PLOD3 is the functional target of circ_003137/PTBP1, thus regulating EMT of glioma cells." (PMID 39431006, 2024). "While PLOD3 is known to be highly expressed in various tumors 47, however, its role in the malignant progression of glioma has not been fully explored." (PMID 39431006, 2024). "Furthermore, the expression levels of several genes (PLOD3, SLC20A1, ADAM9, FBLIM1, SPOCD1, P4HB, PROS1 and SELENON) were positively correlated with glioma grades." (PMID 32091665, 2020). "Significantly higher PLOD3 expression was found in WHO pathological grade IV (n = 81) than in pathological grade II gliomas (n = 7; p = 0.0046) and non-tumor controls (n = 23; p = 5.3 × 10–9)." (PMID 29644003, 2018). "The PLOD3 level was also elevated in WHO grade III gliomas than in non-neoplastic brain tissues (n = 23; p = 0.0178)." (PMID 29644003, 2018). "The anti-angiogenesis effect of PLOD3 may depend on disarrangement of collagen alignment in glioma, which has been observed in an in vivo xenograft study with knockdown of PLOD2, the other PLOD3 isoform." (PMID 29644003, 2018). "PLOD3 expression was evaluated with real-time PCR in glioblastoma (GBM) cell lines and by Gene Expression Omnibus dataset analysis and immunohistochemistry of glioma tissues." (PMID 29644003, 2018). "PLOD3 overexpression was correlated with negative survival in glioma patients." (PMID 29644003, 2018).
lung carcinoma (15 papers, 2018 to 2025). "To completely elucidate the mechanisms underlying PLOD3-induced lung cancer cell migration and invasion, we further investigated the MAPK-associated signaling pathways in cellular invasion." (PMID 30442941, 2018). "PLOD3 was also linked to ER stress in human lung cancer models and mice models." (PMID 35627171, 2022). "Furthermore, we analyzed the association between PLOD3 expression and the pathological grade of lung cancer, using patient samples." (PMID 30442941, 2018). "Moreover, PLOD3 upregulation is associated with reduced overall survival in lung cancer and gastric cancer patients, and PLOD3 serves as a prognostic marker in these patients." (PMID 30442941, 2018). "However, the mechanism underlying PLOD3-mediated upregulation of MMPs and the signaling pathway by which PLOD3 regulates lung cancer cell metastasis remain unknown." (PMID 30442941, 2018). "Hence, it is important to understand whether PLOD3 plays a role in lung cancer metastasis and its underlying mechanism." (PMID 30442941, 2018). "Despite reports indicating increased expression of PLOD3 in various cancers, for instance, suppressing PLOD3 expression has been found to hinder lung cancer progression by modulating the PKC-delta signaling pathway." (PMID 40133271, 2025). "PLOD3 has also been verified to be connected with colorectal cancer’s progression, lung cancer and ovarian cancer." (PMID 36276080, 2022). "In tumor cells, there is a strong positive correlation between PLOD3 expression and matrix metalloproteinases, which play a sufficient and necessary role in stimulating lung cancer metastasis." (PMID 33807594, 2021). "PLOD3 was also founded in many human solid tumors, containing gastric cancer, lung cancer and hepatocellular cancer." (PMID 33503035, 2021). "We recently identified procollagen-lysine, 2-oxoglutarate 5-dioxygenase 3 (PLOD3), which is involved in fibrosis and tissue remodeling as a radioresistance-related protein in lung cancer cells; however, its mechanism is unclear." (PMID 30770789, 2019). "PLOD3 knockdown overcame chemoresistance and decreased radioresistance by inducing caspase-3-dependent apoptosis in lung cancer cells." (PMID 30770789, 2019). "Here, to develop an anti-tumor reagent, we designed human PLOD3-specific short interfering (si)RNAs to knockdown the endogenous PLOD3 overexpression in lung cancer and then investigate cell proliferation and cell death." (PMID 30770789, 2019). "In the current study, PLOD3 siRNA inhibited the proliferation of lung cancer cells and induced cell death, an effect that was augmented by radiation treatment, in cells and an in vivo model." (PMID 30770789, 2019). "Patients with high PLOD3-expressing lung cancer who were treated with radiotherapy had poorer prognosis than patients with low PLOD3-expressing lung cancer who were treated with radiotherapy in the Kaplan–Meier Plotter database." (PMID 30770789, 2019). "To further investigate the effect of PLOD3 on lung cancer cell metastasis, we evaluated its effects on metastasis." (PMID 30442941, 2018). "Subsequently, PLOD3 expression levels were inversely correlated with reduced survival in lung cancer patients and in multiple human cancer types, including gastric cancers, using Kaplan–Meier plotter analysis." (PMID 30442941, 2018). "In particular, ONCOMINE analysis data indicate that PLOD3 mRNA was upregulated in lung cancer and gastric cancer patients." (PMID 30442941, 2018). "Thereafter, we investigated the effects of PLOD3 overexpression and downregulation on cancer cell invasion and migration in vitro and in vivo, using human lung cancer cell lines and a mouse tumor xenograft model, respectively." (PMID 30442941, 2018). "In this context, we first identified that PLOD3 is one of the most widely upregulated proteins in human lung cancers and observed that PLOD3 upregulation is significantly associated with tumor progression and advanced stages of lung cancer." (PMID 30442941, 2018).